SNORD6 (small nucleolar RNA, C/D box 6)
Synonyms: mgh28S-2412
Gene: Small nucleolar RNA gene on chromosome 11 (93,731,502 to 93,731,574, reverse strand). Ensembl gene ENSG00000202314.
Gene Ontology:
Biological process: RNA processing
Cellular component: nucleolus
Homologues: Orthologues: macaque SNORD6 (97% identical), rabbit SNORD6 (93% identical), pig SNORD6 (92% identical), dog SNORD6 (90% identical), mouse Gm24357 (90% identical), rat Snord6 (90% identical).
Diseases named in the same sentence as SNORD6 in open-access papers:
SNORD6 is named in the same sentence as 4 diseases in open-access papers, as found by Europe PMC text mining. Sharing a sentence is not in itself a finding about the gene and the disease. The quoted sentences say what the papers report.
cervical cancer (2 papers, 2023 to 2025). A primary or metastatic malignant neoplasm involving the cervix. "We established that SNORD6 was associated with poor prognosis in cervical cancer." (PMID 37369687, 2023). "The results showed that the expression of SNORD6 in the cervical cancer tissues was higher than that in the normal cervical epithelial tissues." (PMID 37369687, 2023). "Then, we detected the expression of SNORD6 in the cervical cancer cell lines SiHa and HeLa, and found that the expression level of SNORD6 in the HeLa cells was higher than that in the SiHa." (PMID 37369687, 2023). "Then, the expression level of SNORD6 was detected in 29 normal cervical epithelial tissues and 97 cervical cancer tissues." (PMID 37369687, 2023). "We discovered that SNORD6 expression in cervical cancer tissues was higher than that in normal cervical tissues." (PMID 37369687, 2023). "Histological examinations found that the SNORD6 expression levels in cervical cancer tissues were significantly higher than those in normal cervical epithelial tissues." (PMID 37369687, 2023). "FISH experiments were performed to determine the localization of SNORD6 in the cervical cancer cells." (PMID 37369687, 2023). "Histological examination showed that the expression level of SNORD6 in cervical cancer tissues was higher than that in normal cervical epithelial tissues, suggesting that SNORD6 may play a tumor-promoting role in cervical cancer." (PMID 37369687, 2023). "In addition, the expression of SNORD6 in the cervical cancer tissues in the FIGO stage II–IV was higher than that in stage I." (PMID 37369687, 2023). "Therefore, here, we selected SNORD6 as a research object and explored its role and detailed mechanism in the occurrence and development of cervical cancer." (PMID 37369687, 2023). "Therefore, this study explored whether E6 and E7 are involved in the oncogenic role of SNORD6 in cervical cancer." (PMID 37369687, 2023). "This study preliminarily clarified the biological role and specific mechanism of SNORD6 in the occurrence of cervical cancer, broadening the basic theoretical research of ovarian cancer and may provide a new perspective on the diagnosis and treatment of cervical cancer." (PMID 37369687, 2023).
tumor (2 papers, 2023 to 2025). "Silencing SNORD6 in animal models markedly reduces tumor volume, indicating its potential as a therapeutic target." (PMID 41301542, 2025). "SNORD6 expression was positively correlated with tumor FIGO stage and differentiation." (PMID 37369687, 2023).
cancer (1 paper, 2023). A tumor composed of atypical neoplastic, often pleomorphic cells that invade other tissues. "Therefore, in this study, we explored whether the cancer-promoting effect of SNORD6 is related to the expression of E6 and E7 proteins." (PMID 37369687, 2023). "Therefore, SNORD6 may play a role in promoting cancer by binding to E6 protein." (PMID 37369687, 2023).
SNORD6 also shares sentences with these, for which no sentence is quoted: ovarian carcinoma (1 paper).